CTSW (cathepsin W)
Description:
May have a specific function in the mechanism or regulation of T-cell cytolytic activity. (Microbial infection) Plays a role during influenza virus infection in lungs cells ex vivo. Acts at the level of virus entering host cytoplasm from late endosome.
Synonyms: LYPN
Tractability: Antibody: its Gene Ontology location is reachable by antibodies, with high confidence; UniProt predicts a signal peptide or a membrane-spanning region. PROTAC: ubiquitination databases record sites on it; its protein half-life has been measured.
Gene: Protein-coding gene on chromosome 11 (65,879,809 to 65,883,741, forward strand). Ensembl gene ENSG00000172543.
Subcellular location: Endoplasmic reticulum
Pathways (Reactome):
Hemostasis: Platelet degranulation
Gene Ontology:
Molecular function: cysteine-type peptidase activity
Biological process: immune response; immune system process; proteolysis
Cellular component: endoplasmic reticulum; membrane; extracellular region; lysosome; platelet dense granule lumen; cytoplasm; intracellular organelle lumen
Genetic constraint (gnomAD): Loss-of-function variants: 40 observed, 45.86 expected, observed/expected ratio (o/e) 0.87, 90% interval 0.68 to 1.13. The upper end of that interval is the gene's LOEUF score, 1.13, which puts it in group 4 of 6, group 1 being the genes least tolerant of losing a copy. Missense variants: 468 observed, 494.44 expected, observed/expected ratio (o/e) 0.95, 90% interval 0.88 to 1.02. Synonymous variants: 189 observed, 191.51 expected, observed/expected ratio (o/e) 0.99, 90% interval 0.88 to 1.11.
Homologues: Orthologues: chimpanzee CTSW (99% identical), macaque CTSW (94% identical), dog CTSW (73% identical), rat Ctsw (69% identical), mouse Ctsw (68% identical), pig CTSW (68% identical), guinea pig CTSW (66% identical), Caenorhabditis elegans R09F10.1 (28% identical), zebrafish ctsl.1 (28% identical), Caenorhabditis elegans Y51A2D.8 (26% identical), Caenorhabditis elegans Y113G7B.15 (23% identical), zebrafish ctss1 (23% identical), and 16 more. Paralogues in human: CTSF (36% identical), CTSV (27% identical), CTSL (26% identical), CTSH (25% identical), CTSK (25% identical), CTSO (24% identical), CTSS (23% identical), CTSC (23% identical), CTSB (18% identical), TINAGL1 (18% identical), CTSZ (16% identical), TINAG (15% identical).
Diseases named in the same sentence as CTSW in open-access papers:
CTSW is named in the same sentence as 31 diseases in open-access papers, as found by Europe PMC text mining. Sharing a sentence is not in itself a finding about the gene and the disease. The quoted sentences say what the papers report.
breast cancer (6 papers, 2013 to 2025). A primary or metastatic malignant neoplasm involving the breast. "Together, these results demonstrate that CTSW likely has an important biological function in cancer and that the breast cancer risk allele rs3903072-G is significantly associated with decreased expression of CTSW." (PMID 31507631, 2019). "CTSW encodes a cysteine proteinase highly specific to natural killer (NK) cells and T cells and is potentially involved in regulating their cytotoxity; consistently, CTSW expression negatively correlates with both the risk allele at rs3903072 and the survival probability in breast cancer." (PMID 31507631, 2019). "The genes CXCL9, IL7R, CD79A, and CTSW were selected for their significant associations with overall survival (OS) and recurrence-free survival (RFS) in breast cancer patients." (PMID 40725191, 2025). "CTSW is a candidate tumor-suppressor gene, with expression highly specific to immune cells and also positively correlated with breast cancer patient survival." (PMID 31507631, 2019). "The top SNP, rs3903072, was an eQTL for CTSW in breast cancer." (PMID 37173324, 2023). "In a study of invasive breast cancer (BC) patients with BRCA variants, the expression levels of five metastasis-specific proteins (CTSW, MRS2, SDCB2, RTN4 and RAD23B) were found to correlate with increased overall survival." (PMID 38891048, 2024). "Although not specifically focused on breast cancer, our study also identified CTSW as a SNP-heritable IP component (GCTA V(g)/V(p) = 12.1%) and detected a pan-cancer association with rs3903072 (beta=0.21, p = 2.8e-36)." (PMID 37173324, 2023).
endometrial cancer (5 papers, 2019 to 2023). Primary or metastatic malignant neoplasm involving the endometrium (mucous membrane that lines the endometrial cavity). "A study on endometrial cancer reported that the CTSW gene had a positive correlation with tumor infiltration levels of B cells, CD8 + T cells, CD4 + T cells, macrophages, and dendritic cells." (PMID 37794108, 2023). "In another study, a six-gene prognostic signature, including CTSW, PCSK4, LRRC8D, TNFRSF18, IHH, and CDKN2A, in endometrial cancer was also established using robust likelihood-based survival modeling." (PMID 31781484, 2019). "Currently, CTSW is reported to be a characteristic gene pertinent to the immune microenvironment of breast and endometrial cancers, but neither its specific role nor its mechanism in cancer has been revealed." (PMID 37180113, 2023).
autoimmune disease (2 papers, 2023 to 2024). A disorder resulting from loss of function or tissue destruction of an organ or multiple organs, arising from humoral or cellular immune responses of the individual to their own tissue constituents. "While CTSW expression in lymphocytes has been linked to autoimmune diseases, its role in macrophages is much less studied." (PMID 37073532, 2023). "Our analysis indicated that both subsets showed enhanced cytotoxicity, with sustained increases in expression and chromatin accessibility of key cytotoxic genes such as GZMB, FGFBP2, CTSW, PRF1, which are crucial in other autoimmune disorders." (PMID 39365735, 2024).
epilepsy (2 papers, 2021 to 2025). A brain disorder characterized by episodes of abnormally increased neuronal discharge resulting in transient episodes of sensory or motor neurological dysfunction, or psychic dysfunction. "As shown in our findings, CTSW expression was also downregulated in epilepsy samples." (PMID 40697415, 2025). "CD3D, CD3G, CTSW, and JCHAIN were consistently expressed in the GSE143272 and GSE32534 datasets and all showed a low expression in epilepsy samples." (PMID 40697415, 2025). "Integrated transcriptomic and single-cell sequencing analyses identified CD3D, CD3G, CTSW, and JCHAIN as the key epilepsy genes that were also closely related to T cell function." (PMID 40697415, 2025). "Among them, we observed that the levels of CD3D, CD3G, CTSW, and JCHAIN were all significantly downregulated in epilepsy samples in the GSE143272 and GSE32534 datasets." (PMID 40697415, 2025). "A total of nine hub genes were screened in this study, in particular, four hub genes (CD3D, CD3G, CTSW, and JCHAIN) could effectively distinguish epilepsy samples." (PMID 40697415, 2025). "The PPI showed that there are six resistance genes (CD247, CTSW, IL2RB, MATK, NKG7, and PRF1) that may play a central role in the resistance of epilepsy patients." (PMID 34805265, 2021). "Second, the specific mechanism of the roles of CD3D, CD3G, CTSW, and JCHAIN in the development of epilepsy has not been verified by cell or animal experiments." (PMID 40697415, 2025).
asthma (1 paper, 2020). "The genes of HLA-DRB5, HLA-DQA1, HLA-DPB1, CTSW, PSMB9, and TAP2 have the most number of edges with both predicted genes and childhood-onset asthma-related genes." (PMID 32867763, 2020).
atherosclerosis (1 paper, 2024). A disease characterized by the build-up of fatty material and calcium deposition in the arterial wall resulting in partial or complete occlusion of the arterial lumen. "For example, CTSW has been studied for its role in HDL cholesterol metabolism and its potential impact on atherosclerosis, while STAB1 has been implicated in the clearance of atherogenic lipoproteins." (PMID 38384714, 2024).
chronic myeloid leukemia (1 paper, 2024). "A recent study–case report demonstrated the impact of certain proteins, including CTSW, in the absence of relapse in patients with chronic myeloid leukemia (CML) upon discontinuation of tyrosine kinase inhibitor (TKI) therapy." (PMID 38891048, 2024).
influenza (1 paper, 2022). An acute viral infection of the respiratory tract, occurring in isolated cases, in epidemics, or in pandemics; it is caused by serologically different strains of viruses (influenzaviruses) designated A, B, and C, has a 3-day incubation period, and usually lasts for 3 to 10 days. "Moreover, we show that CTSW knockout (KO) mice display reduced mortality and pathogenicity upon IAV infection and, thus, provide in vivo evidence for the suitability of CTSW as a novel influenza drug target." (PMID 35867415, 2022).
myositis (1 paper, 2018). "We found that PI4KAP1 had a higher expression in CD4+ T cells of HLA-DRB1*03-positive myositis and that TRGC2, CTSW, HPCAL4, ZNF683, and GOLGA8B had a higher expression in CD4+ T cells of HLA-DRB1*03-negative myositis patients." (PMID 30157932, 2018). "PI4KAP1 was found to have a higher expression in CD4+ T cells of HLA-DRB1*03-positive patients with myositis, and TRGC2, CTSW, HPCAL4, ZNF683, and GOLGA8B were found to have a higher expression in CD4+ T cells of HLA-DRB1*03-negative patients with myositis." (PMID 30157932, 2018).
renal carcinoma (1 paper, 2019). A carcinoma arising from the epithelium of the renal parenchyma or the renal pelvis. "Finally, it has been recently shown that an elevated level of CTSW expression is observed in CD8+ T cells with enhanced immunity against bacterial infection and cancer, as well as in renal cancer with high lymphocyte infiltration." (PMID 31507631, 2019).
vitiligo (1 paper, 2020). Generalized well circumscribed patches of leukoderma that are generally distributed over symmetric body locations and is due to autoimmune destruction of melanocytes. "In dogs, we found enrichment of T cell gene signatures, with upregulation of IFNG, TNF, PRF1, IL15, CTSW, CXCL10, and CCL5 in both VKH and vitiligo in dogs compared to healthy controls." (PMID 33384688, 2020).
tumor (12 papers, 2019 to 2025). "Nomura and Katunuma44 found that CTSW, a member of the cathepsin protease family, is closely associated with tumour invasion, metastasis and proliferation by degrading the extracellular matrix and basement membrane." (PMID 39783847, 2025). "The CTSW protein is a candidate tumor‐suppressor gene expressed by natural killer and cytotoxic T‐cells." (PMID 37415393, 2025). "In other tumor types, CTSW has been reported as a candidate tumor suppressor gene, with expression positively correlated with patient survival and conferring a strong prognostic value." (PMID 37415393, 2025). "In our study, analysis of the TCGA database predictions revealed a significantly lower expression of CTSW in tumor cells compared to normal cells." (PMID 37349706, 2023). "ITGAE is associated with a group of genes that have a cytotoxic function in CD8 cytotoxic T cells (CTSW, GNLY, NKG7, PRF1, GZMB, KLRK1) up-regulated in the tumor, identifying resident CD8 T cells in the tumor to have a highly cytotoxic and activated phenotype." (PMID 39548591, 2024). "We found that the expressions of CCL1, FABP7, S100B, CTSW, and SEZ6 significantly decreased in the tumor tissue, the expression of CPLX2 and SPIB increased obviously in BC." (PMID 36581948, 2022). "The downregulated expression of IL-1, CTSW, NR1H3 and CCR8 (with HR < 1) indicated these molecules as tumor suppressors, whereas the upregulated expression levels of LY86, RABGEF1, CYFIP2 and SERINC3 (with HR > 1) indicated these molecules as oncogenes." (PMID 33816214, 2020). "Tumor-specific IL-7Rhi CD8+ T cells (cluster 4) expressed intrinsic cytotoxic mediators including natural killer cell granule protein 7 (Nkg7), killer cell lectin receptor D1 (Klrd1), cathepsin W (Ctsw), cystatin F (Cst7), and Ccl5, suggesting a capacity for cytotoxicity." (PMID 37459511, 2023).
cancer (5 papers, 2019 to 2024). A tumor composed of atypical neoplastic, often pleomorphic cells that invade other tissues. "This review aims to summarize the current state of knowledge of CTSF and CTSW biology, highlighting their distinct evolutionary pathways despite shared features such as potential anti-cancer activity and involvement in immune regulation." (PMID 38891048, 2024). "Notably, we saw that genes implicated in cancer risk were mainly those involved in both MHC Class I and Class II antigen processing and presentation, while TIME eQTLs associated with prognosis pointed to genes that would support evasion of the MHC I CD8+ T cell axis including PD-L1, PD-1, and CTSW." (PMID 37173324, 2023). "However, the large number of in vitro and in vivo experiments and bioinformatic analyses of the molecular mechanisms of CTSW and CTSF still do not provide a clear explanation of the role of CTSW and CTSF in the immune response to cancer." (PMID 38891048, 2024).
infection (2 papers, 2022 to 2024). The state of being infected such as from the introduction of a foreign agent such as serum, vaccine, antigenic substance or organism. "Heterogeneous nuclear ribonucleoprotein D (HNRNPD), epsin 2 (EPN2), and tripeptidyl peptidase 1 (TPP1), among others, showed reduced protein levels when cotransfected with CTSW compared to their levels in the green fluorescent protein (GFP) control, regardless of infection." (PMID 35867415, 2022).
CTSW also shares sentences with these, for which no sentence is quoted: autoimmune disorders (1 paper); bacterial infection (1); breast tumor (1); colitis (1); COVID-19 (1); familial hypercholesterolemia (1); head and neck squamous cell carcinoma (1); lung carcinoma (1); melanoma (1); nematode infection (1); non-small cell lung carcinoma (1); osteoporosis (1); pancreatic cancer (1); polycystic ovary syndrome (1); psoriasis (1); Sepsis (1); T-cell lymphoma (1).